PEX11B (peroxisomal biogenesis factor 11 beta)
Description:
Involved in peroxisomal proliferation. May regulate peroxisome division by recruiting the dynamin-related GTPase DNM1L to the peroxisomal membrane. Promotes membrane protrusion and elongation on the peroxisomal surface.
Synonyms: PEX11-beta; PEX11beta; PEX11β; PEX14B
Tractability: Antibody: UniProt predicts a signal peptide or a membrane-spanning region. PROTAC: ubiquitination databases record sites on it; its protein half-life has been measured.
Gene: Protein-coding gene on chromosome 1 (145,911,349 to 145,918,730, reverse strand). Ensembl gene ENSG00000131779.
Subcellular location: Peroxisome membrane
Subcellular location (Human Protein Atlas): Vesicles; Nucleoplasm
Pathways (Reactome):
Protein localization: Class I peroxisomal membrane protein import
Gene Ontology:
Molecular function: identical protein binding; protein binding; protein homodimerization activity
Biological process: peroxisome fission; peroxisome organization; regulation of peroxisome size; signal transduction
Cellular component: membrane; peroxisomal membrane; peroxisome; protein-containing complex; cytosol; mitochondrion
Genetic constraint (gnomAD): Loss-of-function variants: 14 observed, 20.31 expected, observed/expected ratio (o/e) 0.69, 90% interval 0.45 to 1.08. The upper end of that interval is the gene's LOEUF score, 1.08, which puts it in group 4 of 6, group 1 being the genes least tolerant of losing a copy. Missense variants: 270 observed, 287.44 expected, observed/expected ratio (o/e) 0.94, 90% interval 0.85 to 1.04. Synonymous variants: 118 observed, 119.62 expected, observed/expected ratio (o/e) 0.99, 90% interval 0.85 to 1.15.
Gene-disease validity (ClinGen):
ClinGen rates the evidence that PEX11B causes each of these diseases.
peroxisome biogenesis disorder (autosomal recessive): Definitive.
Homologues: Orthologues: chimpanzee PEX11B (100% identical), rabbit PEX11B (97% identical), guinea pig PEX11B (94% identical), macaque PEX11B (93% identical), mouse Pex11b (93% identical), rat Pex11b (93% identical), pig PEX11B (90% identical), dog PEX11B (90% identical), zebrafish pex11b (64% identical), tropical clawed frog pex11b (62% identical), Drosophila melanogaster Pex11ab (31% identical). Paralogues in human: PEX11A (40% identical).
Diseases named in the same sentence as PEX11B in open-access papers:
PEX11B is named in the same sentence as 26 diseases in open-access papers, as found by Europe PMC text mining. Sharing a sentence is not in itself a finding about the gene and the disease. The quoted sentences say what the papers report.
peroxisome biogenesis disorder (7 papers, 2015 to 2025). "PEX11β ([OMIM] 614920) mutation causes an extremely rare subgroup of peroxisomal biogenesis disorders, with only six cases reported to date." (PMID 33558817, 2021). "Confirming the importance of peroxisome dynamics for neuronal health, multiple PEX11β-deficient patients have been identified, presenting with neurological symptoms reminiscent of a mild peroxisomal biogenesis disorder, despite mainly normal biochemical parameters." (PMID 40621503, 2025). "The lowered respiratory chain complex IV-staining intensity that we have observed in the Pex11b-knockout mouse molars suggested a disturbance of mitochondrial function, typical for severe peroxisomal disorders." (PMID 39652567, 2024). "Although mitochondrial alterations and mistargeting of peroxisomal proteins to mitochondria have been observed in peroxisome biogenesis disorders, it remains to be established whether PEX11β mistargeting contributes to the pathophysiology of PEX19-deficiency and related disorders." (PMID 35678336, 2022). "Mutations in PEX11B have been associated with peroxisome biogenesis disorders (PBDs), and studies on animal models lacking either PEX11A or PEX11B have provided significant insights into peroxisome biology." (PMID 38753762, 2024).
Zellweger syndrome (4 papers, 2015 to 2025). "In the current study we analyzed the impact of a severe peroxisomal defect on odontogenesis using the Pex11b knockout mouse as an experimental model for the Zellweger syndrome." (PMID 39652567, 2024). "Interestingly, Pex11a knockout mice are viable until adulthood while the Pex11b knockout animals display similar symptoms as Zellweger syndrome patients." (PMID 39652567, 2024). "Zellweger spectrum disorders (ZSDs), including archetypal Zellweger syndrome, neonatal adrenoleukodystrophy (NALD) and infantile Refsum disease (IRD), are PBDs caused by mutations in peroxin genes (PEX1, PEX2, PEX3, PEX5, PEX6, PEX10, PEX11β, PEX12, PEX13, PEX14, PEX16, PEX19 or PEX26)." (PMID 40949164, 2025).
diabetic neuropathy (2 papers, 2025). A chronic, pathological complication associated with diabetes mellitus, where nerve damages are incurred due to diabetic microvascular injury involving small blood vessels that supply these nerves, resulting in peripheral and/or autonomic nerve dysfunction. "Peroxiredoxin-6 (PRDX6) and PEX11B palmitoylation can affect diabetic neuropathy." (PMID 40959086, 2025).
asthma (1 paper, 2022). "Higher levels of blood DNA-methylation of a CpG site in Peroxisomal Biogenesis Factor 11 Beta were associated with asthma remission." (PMID 35197433, 2022).
COVID-19 (1 paper, 2025). A disease caused by infection with severe acute respiratory syndrome coronavirus 2. "Suppressed PEX3, PMP70 and PEX14 immunolabeling in vitro.Suppressed PEX3, PEX11β, PEX5L and PEX14 mRNA levels and decreased PMP70 and PEX14 protein levels in brain tissue from COVID-19 patients versus controls.Suppressed Pex3 mRNA and catalase protein in brains from infected hamsters." (PMID 40949164, 2025).
depression (1 paper, 2010). "Peroxisomal biogenesis factor 11b (Pex11b) showed the highest increased expression in both P/FC and HIP of the FSL animals, but has not been directly linked to depression previously." (PMID 20830301, 2010).
developmental delay (1 paper, 2015). "As noted, null mutations of Adar and Pex11b are associated with developmental delay." (PMID 26552429, 2015).
HIV-1 infection (1 paper, 2020). The type species of lentivirus and the etiologic agent of acquired immunodeficiency syndrome (AIDS). "Seventy-two hours later, the relative levels of four peroxisomal biogenesis factors (PEX2, PEX7, PEX11B, and PEX13) that are downregulated during HIV-1 infection of human cells were assessed by immunoblotting." (PMID 32127461, 2020).
leiomyosarcoma (1 paper, 2008). An uncommon, aggressive malignant smooth muscle neoplasm, usually occurring in post-menopausal women. "Of these, two genes, PRKAR2B on chromosome 7 and PEX11B on chromosome 1 showed gains of approximately 5-fold by their respective Stouffer Z scores, and expression levels that were significantly higher in GIST compared to leiomyosarcomas." (PMID 19259404, 2008).
melanoma (1 paper, 2021). A malignant, usually aggressive tumor composed of atypical, neoplastic melanocytes. "ATP6V0C and PEX11B, proteins regulated by USP7, were confirmed in both melanoma cell lines by western blot." (PMID 33869052, 2021). "Furthermore, proteomic data analysis and western blot results showed the importance of the classical signaling pathways PI3K/Akt/FOXO and AMPK, and that new biological processes involve proteins such as ATP6V0C, CASP7, and PEX11B, which play crucial roles in USP7 mediating melanoma growth." (PMID 33869052, 2021).
multiple sclerosis (1 paper, 2023). A progressive autoimmune disorder affecting the central nervous system resulting in demyelination. "The peroxisome proliferator phenylbutyrate reversed the inflammation-induced decrease in ABCD3/PMP70, PEX11β and catalase protein levels and is recommended as a possible drug for treatment of multiple sclerosis." (PMID 37170361, 2023).
thyroid cancer (1 paper, 2017). "In thyroid cancers, the expression of peroxisomal-biogenesis genes PEX7, PEX11B and PEX19 was significantly increased by energy metabolism." (PMID 28582771, 2017).
infection (5 papers, 2017 to 2025). The state of being infected such as from the introduction of a foreign agent such as serum, vaccine, antigenic substance or organism. "The loss of multiple PEX proteins was evident at 24-h post-infection; however, by 48-h, the reduction in PEX3, PEX7, PEX11B, PEX13 and PEX19 was much more pronounced." (PMID 31311201, 2019). "Immunoblotting revealed that infection of primary macrophages, a physiologically relevant cell type in HIV patients, resulted in dramatic loss of PEX2, PEX7, PEX13, and to a lesser extent, PEX11B." (PMID 28594894, 2017). "In a subsequent study, the authors suggest a model by which vMIA activates PEX11β, which in turn induces MFF to upregulate peroxisome fission during infection." (PMID 35445031, 2022). "Infection with an isogenic Nef knockout virus had a similar effect on PEX2, PEX7, PEX13, and PEX11B as wild-type HIV-1." (PMID 32127461, 2020). "Unlike wild-type HIV-1, infection with Vpu-S52,56D and Vpu-S52,56N viruses did not result in a significant loss of PEX2, PEX7, PEX11B, or PEX13 in HeLa-CD4/CXCR4/CCR5 cells, macrophages, or T cells." (PMID 32127461, 2020). "Expression of peroxisome biogenesis-related transcripts such as PEX14, PEX5, and PEX11B were not altered after 6 and 12 h of STM infection." (PMID 39695325, 2025).
tumor (5 papers, 2008 to 2025). "In contrast, analysis for mRNAs encoding for peroxisomal biogenesis proteins (Pex7, Pex10, Pex12), and proteins for peroxisomal proliferation (Pex11α, Pex11β) were significantly upregulated in PMA tumor compared to control tissue." (PMID 34360635, 2021). "One tumor (GIST199) showed 3–4 PEX11B signals/nucleus and the other (GIST159) 2–3 copies." (PMID 19259404, 2008). "In mechanistic terms, tegaserod maleate reduces proteins levels of the peroxisome membrane proteins PEX11B and PEX13, affecting the function of peroxisomes and achieving tumor suppression." (PMID 34422635, 2021). "Simultaneously, we detected the expression of PEX11B, PEX13 and PMP70 in tumor tissues by western blotting." (PMID 34422635, 2021). "We further explored the role of PEX11B and PEX13 in tumor suppression." (PMID 34422635, 2021).
neurodegenerative disease (1 paper, 2022). A disorder of the central nervous system characterized by gradual and progressive loss of neural tissue and neurologic function. "This experiment demonstrates that MFF-deficient human fibroblasts could represent a suitable model to analyse the impact of PEX11β mutations on peroxisome fission in a neurodegenerative disease." (PMID 35678336, 2022).
neurological disorder (1 paper, 2015). "Recently, it was found that a mutation in one of the three mammalian paralogs, PEX11β, results in a neurological disorder." (PMID 25769804, 2015).
PEX11B also shares sentences with these, for which no sentence is quoted: peroxisome biogenesis disorder 14B (2 papers); brain diseases (1); breast carcinoma (1); Breast Invasive Carcinoma (1); hepatoblastoma (1); hypothyroidism (1); leukemia (1); Seckel syndrome (1); Stroke (1); viral infection (1).